AHR (aryl hydrocarbon receptor)
Diseases named in the same sentence as AHR in open-access papers (continued):
Sharing a sentence is not in itself a finding about the gene and the disease.
cancer (continued). "Resolving this apparent contradiction is of considerable importance given the drive to use AHR “modulators” to treat various cancers." (PMID 29735912, 2018). "Here we found elevated AhR level in the nucleus linked with radioresistance in LC and NPC cells, indicating that activation of AhR contributes to cancer progression, stem-like properties, and radioresistance." (PMID 29706625, 2018). "In contrast, the AHR has been reported to exhibit anti-tumorigenic effects in prostate, stomach liver pancreatic, and breast cancers." (PMID 29735912, 2018). "HIF‐1β predominately binds HIF‐1α or aryl hydrocarbon receptor (AhR) to form heterodimer complexes that regulate transcription of target genes involved in various physiological and pathological processes, including cancer." (PMID 29926531, 2018). "In a corollary to these studies, an accumulating body of evidence indicates that the AHR is important in the progression of a variety of cancer types." (PMID 29735912, 2018). "Emerging evidence suggests the promoting role of the AhR in the initiation, promotion, progression, invasion, and metastasis of cancer cells." (PMID 29487603, 2018). "The potential function of the AhR in carcinogenesis in different types of cancer has been explored for several years." (PMID 29487603, 2018). "Some studies suggested that several types of human cancer cells showed higher numbers of copies of the AhR than normal cells." (PMID 29487603, 2018). "After several decades of scrutiny as a xenobiotic sensor, the AHR is now being evaluated as a novel target for cancer and immuno-therapy." (PMID 29735912, 2018). "In general, these studies add further incentive for the use of AHR inhibitors in breast and, potentially, other cancers especially given the high level of AHR expression and chronic activity in a wide variety of cancers." (PMID 29735912, 2018). "AhR is a key target for dioxin-like compounds, which is related to these compounds’ potential to induce cancer and a wide range of endocrine and immune system-related effects." (PMID 29127629, 2018). "Here we show that nuclear IKKα targets the promoters of stem-like genes as a partner of AhR, contributing to radioresistance, indicating a critical role of nuclear IKKα in cancer progression and radioresistance." (PMID 29706625, 2018). "The aryl hydrocarbon receptor (AHR) is a ligand-activated transcription factor with important functions in the immune response and cancer." (PMID 29563571, 2018). "There is growing interest in manipulating the AHR to modulate the function of immune system to alleviate the progression of immune-mediated diseases and treat cancer." (PMID 29379138, 2018). "Resolving this apparent contradiction is critical to the design of AHR-targeted cancer therapeutics." (PMID 29735912, 2018). "At molecular level, resveratrol plays pleiotropic effects including inhibition of kinases, anti-inflammatory, analgesic and anti-cancer activities, and detoxification, by inhibiting the aryl hydrocarbon and dioxin receptor (AhR)." (PMID 29721498, 2018). "Together, these data underscore the importance of further studying the role of AhR-signaling in the context of cancer biology as a putative therapeutic target." (PMID 30429474, 2018). "We have postulated that the aryl hydrocarbon receptor (AHR) drives the later, more lethal stages of some cancers when chronically activated by endogenous ligands." (PMID 29735912, 2018). "We further found the aryl hydrocarbon receptor signaling pathway plays an important role in the initiation of smoking-attributable cancer." (PMID 28500316, 2017). "Consistent with our previous report, our finding suggests that raloxifene-based compounds have the potential to be developed as AhR selective anti-cancer agents." (PMID 29194351, 2017). "We conclude that Y134 is a promising raloxifene analog for further optimization as an anti-cancer agent targeting the AhR." (PMID 29194351, 2017).
cancer (continued). "It was demonstrated that the AHR pathway is required for carcinogen-induced cancer in murine models." (PMID 28453567, 2017). "The Aryl hydrocarbon receptor (AhR) is a cytosolic ligand-activated transcriptional factor that is involved in the regulation of cell differentiation, proliferation, and cancer imitation." (PMID 28103884, 2017). "One such compound, kynurenine, was shown to have a net immunosuppressive effect on the proliferative capacity of inflammatory T cells, whereas others have been shown to activate the AHR and induce an pro-inflammatory response in cancer cells." (PMID 29190885, 2017). "Although dioxin is classified as a human carcinogen- acting through the AhR- there is controversy for the role of the AhR in cancer development." (PMID 28079158, 2017). "Experimental models revealed the involvement of oxidative stress, DNA methylation, formation of DNA adducts, and Aryl hydrocarbon receptor activation as the key mechanisms of soot- and CB-induced cancers." (PMID 28713383, 2017). "Our understanding of the AhR and its role in carcinogenesis continues to evolve, and has recently started to receive a great deal of interest as a molecular target for anti-cancer drugs." (PMID 29194351, 2017). "We previously showed that raloxifene decreases cancer cell viability by inducing apoptosis in an AhR-dependent manner." (PMID 29194351, 2017). "Many of the toxic effects of TCDD exposure, including chloracne, immunosuppression, hepatotoxicity and cancer, are mediated by the AHR." (PMID 28086803, 2017). "Whereas AhR mediates the metabolism of xenobiotic and endogenous compounds, its novel function in cancer epithelial-mesenchymal transition (EMT) remains controversial." (PMID 28195146, 2017). "Abnormal expression or activity of AHR has been highlighted in malignant tumor progression in the past few years." (PMID 27752740, 2017). "In conclusion, we showed that raloxifene analogE/Y134 is an AhR agonist with AhR-dependent anti-cancer effects." (PMID 29194351, 2017). "The important roles of AHR in immunosuppression, metabolic diseases, and cancer development via crosstalk with multiple signaling pathways have been recognized by several recent studies." (PMID 28878246, 2017). "Specifically, we evaluated these compounds for their ability to induce AhR-mediated gene transcription and inhibit cancer cell growth through a mechanism requiring AhR expression." (PMID 29194351, 2017). "We present data that the 4-hydroxyphenyl benzothiophene core is important for activating the AhR, and is critical for AhR-mediated raloxifene-induced anti-cancer effects." (PMID 29194351, 2017). "Together, these data suggested that analog E, which is well tolerated in zebrafish embryos, also has AhR-dependent anti-cancer effects." (PMID 29194351, 2017). "Taken together, these data clearly demonstrate that the AHR protein resident in the cytoplasm can prevent the expression of mesenchymal markers and downregulate cancer cell metastasis." (PMID 27752740, 2017). "Identifying selective AhR modulators that produce desirable clinical outcomes represents an opportunity for developing new anti-cancer agents." (PMID 28424418, 2017). "Using small molecule screening approaches, we have previously identified compounds with anti-cancer effects that function through the AhR." (PMID 29194351, 2017). "The aryl hydrocarbon receptor (AhR) is a potential clinical target for cancer and autoimmune dysfunction." (PMID 28424418, 2017). "An increased expression and activity of AhR in inflammatory disease as well as in various tumors and cancer cell lines has been reported and the critical role of AhR in tumorigenesis is well established." (PMID 26862745, 2016). "ARNT has been shown to regulate the anti-oxidant response and resistance to chemotherapeutic drugs in diverse cancers and is important for AHR or HIF-1 promoted tumors." (PMID 26909609, 2016).
cancer (continued). "If metabolic activation of the organic molecules increased the levels of their adducts with DNA thus promoting cancer initiation, anticancer drug- or toxin-induced AhR activation played a pivotal role in cancer promotion and progression." (PMID 26881027, 2016). "The novel roles of tryptophan derivatives (e.g., ITE), together with the likely implication of the AhR pathway in regulating cell stemness, open interesting new therapeutic avenues to target stem-like cancer cells." (PMID 27243009, 2016). "Because of demonstrated unequivocal involvement in smoking-induced cancer in laboratory animals, four candidate genes––AHR, CYP1A1, CYP1A2, and CYP1B1––were selected for a clinical genotype-phenotype association study of HNSCC risk in smokers." (PMID 27894333, 2016). "Recent studies identified a role for the aryl hydrocarbon receptor (AHR), an environmental carcinogen receptor implicated in cancer initiation, in normal tissue-specific stem cell self-renewal." (PMID 26984638, 2016). "Based on our findings, we suggest that PKM2 sensitizes AhR-mediated detoxification in cancer cells and fetal cells to ensure proliferation, and propose a ‘local acetyl-CoA production’ model for transcriptional activation." (PMID 26405201, 2016). "We also detected for the first time in RAJI cells the presence of a GGGGC(2×) repeat insertion in the Sp1 region of AHR promoter (SNP rs71010234), a SNP previously reported for other cancer cell lines and human samples." (PMID 27006469, 2016). "It is expected that the results from those inquiries will place AHR at the center of studies about stem cell metabolism and its impact on aging, regeneration, and cancer stem cells." (PMID 27563312, 2016). "The data presented here strongly suggest that the AHR drives tumorigenesis in part through induction or maintenance of cells with cancer stem cell-like properties." (PMID 26984638, 2016). "This study also revealed that AHR induces differentiation in human carcinoma cells and that its downmodulation promotes undifferentiation." (PMID 27243009, 2016). "At TFBS, hypermethylated DMRs were enriched for several TFs, most notable of which were the ligand activated and cancer-associated AHR, the development-associated PAX5 and cell cycle/cancer-related E2F family members." (PMID 25960784, 2015). "Taken together, our work reveals a novel role of tryptophan derivatives (in particular ITE) and the AhR pathway in regulating cell stemness and opens a new therapeutic avenue to target stem-like cancer cells." (PMID 26059097, 2015). "We overlaid pathways generated for Cancer, Cell Proliferation, Hematopoiesis and Cell Migration, and AhR." (PMID 26208102, 2015). "Here, in cancer stem cells, AhR is shown to be activated by the tryptophan derivative ITE, which causes transcriptional repression of Oct4 and reduced tumorigenesis." (PMID 26059097, 2015). "Novel aspects of IGF1R/IR in cancer, such as biased agonism, integrin β3 signaling, AHR, and new therapeutic targeting strategies will be discussed." (PMID 25699021, 2015). "More recently, potential roles of the AhR and its synthetic ligands in stem cell and cancer stem cell biology start to be appreciated." (PMID 26059097, 2015). "Our findings reveal a previously unidentified connection between AhR and Oct4 in human pluripotent stem cells and cancer cells." (PMID 26059097, 2015). "The aryl hydrocarbon receptor, AhR, can regulate Oct4, which is often expressed in cancer stem cells and promotes pluripotency and tumorigenesis." (PMID 26059097, 2015). "Recent reports described the impact of inflammatory IDO activation and aryl hydrocarbon receptor- (AhR-) mediated pathways on the development of LPS tolerance and immune escape of cancer cells." (PMID 26881062, 2015).
cancer (continued). "Taken together, our findings indicate that a novel agent YL-109 inhibits cell growth and metastatic potential by inducing CHIP expression through AhR signaling and reduces cancer stem cell properties in MDA-MB-231 cells." (PMID 25403352, 2014). "AHR activation has been link to cancer and is also believed to promote the development of a Th17 response." (PMID 24663285, 2014). "Ingenuity pathway analysis (IPA) revealed 4 canonical pathways significantly dysregulated in the transformed cells trMCF clone 11: aryl hydrocarbon receptor signaling, retinoic acid activation, xenobiotic metabolism signaling and molecular mechanism of cancer." (PMID 24676586, 2014). "With regard to AhR, azole antifungal drugs were shown to influence AhR-dependent genes in aquatic species, rodents and in murine and human cancer cell lines." (PMID 25000292, 2014). "Inhibition of the AHR–IL-6–STAT3 signaling loop restored T-cell proliferation in mixed leukocyte reactions performed in the presence of IDO-expressing human cancer cells." (PMID 24657910, 2014). "Although expressed in normal tissues, elevated AhR expression has been reported in several cancer types including lung, breast, liver, stomach and pancreas." (PMID 24932473, 2014). "We evaluated the antiperitoneal dissemination potential of knockdown AhR and Biseugenol in cancer mouse model and assessed mesenchymal characteristics." (PMID 25226618, 2014). "Although previous studies suggest that AhR possesses different functions, the role of AhR in cancer cells and in regulating peritoneal dissemination remains poorly understood." (PMID 25226618, 2014). "In summary, these data indicate that constitutive IDO expression in human cancer cells is sustained by its own enzymatic product - kynurenine - via an AHR–IL-6–STAT3 autoactivation loop." (PMID 24657910, 2014). "Several challenges have to be met in developing AHR antagonists to cancer immunotherapy: first, the AHR is a promiscuous receptor binding several structurally diverse molecules with different affinity." (PMID 25628622, 2014). "It was described that KET and other antifungal drugs are inducers of CYP1A genes in human and murine cancer cell lines, tentatively through an AhR-dependent mechanism." (PMID 25000292, 2014). "Recently, scientists found that AhR activation seems to be also important for cancer and inflammation, supporting the possibility of targeting the AhR for therapy in inflammation and a number of cancers." (PMID 23434865, 2013). "Aryl hydrocarbon receptor (AhR) not only regulates drug-metabolizing enzyme expression but also regulates cancer malignancy." (PMID 24330582, 2013). "In AF-sensitive cancer cells, the AhR is present in the cytoplasm as a component of a complex with the chaperone heat shock protein (Hsp90)." (PMID 24058584, 2013). "Conversely, in AF-resistant cancer cells, the AhR is localized in the nucleus, and AF cannot activate the AhR pathway." (PMID 24058584, 2013). "Lines of evidence suggest that AhR has important roles in cancer pathogenesis, promotion, and malignancy." (PMID 24330582, 2013). "The aryl hydrocarbon receptor (AHR) is a ligand-activated transcription factor that has been explored as a therapeutic target for cancer." (PMID 24171117, 2013). "The more recently emerging role of AhR in protein degradation via CUL4B/AhR-mediated ubiquitylation and consequently cancer suppression is also of potentially related significance." (PMID 23656719, 2013). "Not only can the AhR be targeted independently, it can be targeted in combination with other cancer treatments, such as chemotherapy or radiation therapy." (PMID 25068070, 2013). "Lastly, we evaluated AhR expression among 967 cancer cell lines using the newly developed Cancer Cell Line Encyclopedia." (PMID 22815870, 2012).
cancer (continued). "Within the AML Signalisome, there is a significant enrichment for genes involved in AhR signaling, as well as functional enrichment for cellular development, cancer, hematological system development/function, and hematopoiesis." (PMID 22754483, 2012). "A novel and clinically important role for the AhR as a target for anti-cancer therapies has emerged from its classically studied role as a mediator of the effects of environmental toxins such as 2,3,7,8-tetrachlorodibenzo-p-dioxin (TCDD)." (PMID 22815870, 2012). "The molecular target(s) of tranilast in cancer have been unclear, but we demonstrate here that it is an aryl hydrocarbon receptor (AHR) agonist." (PMID 21072210, 2010). "This suggests that AHR agonists (including some environmental contaminants) have anti-cancer effects against some types of tumors but, as a note of caution, they have also been shown to exert carcinogenic effects." (PMID 21072210, 2010). "We detected high AhR expression and activation in basal cells and atrophic epithelial cells of human cancer bearing prostates." (PMID 20140206, 2010). "Collectively, these results provide a framework for future studies to manipulate the AhR for cancer chemoprevention." (PMID 20565777, 2010). "Our novel findings demonstrate previously unidentified roles of cAMP response element-binding protein (CREB) and the aryl hydrocarbon receptor (AhR) in the regulation of fascin-1 transcription in human carcinoma cells." (PMID 19340314, 2009). "In summary, AHR plays a highly versatile and context-sensitive role in cancer." (PMID 41540003, 2026). "In tumors where AHR activation protects against ferroptosis, AHR inhibition could sensitize cancer cells to this form of cell death and hence offer novel therapeutic strategies." (PMID 41540003, 2026). "Understanding the mechanisms by which these factors regulate the AhR-mediated carcinogenic process may assist scientists and clinicians in developing personalized therapies aimed at slowing cancer progression and improving patient survival outcomes." (PMID 40141386, 2025). "Through its ability to respond to both environmental toxins and endogenous signals, AhR is involved in many critical physiological processes, and its dysregulation can contribute to various diseases, including cancer, autoimmune disorders, metabolic diseases, and neurodegenerative conditions." (PMID 39940973, 2025). "In vitro experiments in human colon cancer cells, agonist stimulation of the AhR may mediate cancer cell cycle arrest." (PMID 40291905, 2025). "This suggests that AHR may exert opposing effects in different cellular environments, further complicating its role in cancer biology." (PMID 40303305, 2025). "Exercise-induced reductions in IDO, KYN, and AhR expression may therefore enhance immune responses in cancer patients." (PMID 40115437, 2025). "In contrast, the presence of an AHR antagonist in the gut may be of use from a therapeutic standpoint in specific situations, such as cancer treatment." (PMID 40077746, 2025). "Furthermore, GPC5 is pivotal in orchestrating the initiation, proliferation, migration, and invasion of cancer cells by activating signaling pathways such as Wingless/Integrated (Wnt), aryl hydrocarbon receptor (AHR) and Hedgehog." (PMID 40352786, 2025). "Our data suggest that FRA1 is upregulated through AHR activation which may contribute to reduced cancer cell viability." (PMID 40493189, 2025). "AHR belongs to the basic helix–loop–helix–(bHLH) superfamily of transcription factors, which regulates biological processes responsible for maintaining tissue homeostasis or contributing to inflammation and cancer development." (PMID 40332338, 2025). "Since CYP1B1 gene expression is influenced by exogenous activation of the AhR pathway by PAHs and related environmental pollutants, its expression in cancer patients may vary depending on lifestyle and environmental exposures." (PMID 41009721, 2025).